ORC6 (origin recognition complex subunit 6)
Diseases named in the same sentence as ORC6 in open-access papers (continued):
Sharing a sentence is not in itself a finding about the gene and the disease.
cancer (17 papers, 2008 to 2024). A tumor composed of atypical neoplastic, often pleomorphic cells that invade other tissues. "One key protein, origin recognition complex subunit 6 (ORC6), which is critical for cell replication and has been implicated in various cancers, showed a substantial reduction in the CER and NER compartments." (PMID 39677520, 2024). "Further bioinformatics scrutiny revealed that genes co-expressed with ORC6 are enriched in multiple signaling cascades linked to cancer." (PMID 38971772, 2024). "Further bioinformatics investigation unveiled that ORC6 co-expressed genes are enriched in signaling pathways intricately linked to cancer." (PMID 38971772, 2024). "In conclusion, our study revealed that high expression of ORC6 is generally linked to unfavorable prognosis in the majority of cancer types, and it has good diagnostic value." (PMID 37901236, 2023). "The research found that ORC6 was frequently overexpressed in various cancer types and was associated with adverse survival outcomes." (PMID 37901236, 2023). "Aberrations in ORC6 expression or functionality have been associated with various cancer types, contributing to increased cell proliferation and potentially influencing poor prognosis in certain malignancies such as breast, lung, colorectal, and hepatocellular carcinomas." (PMID 38971772, 2024). "Prior studies have linked high ORC6 expression to poor tumor prognosis, progression, and drug resistance in some cancers, but its prognostic and biological significance in most cancer types remains unclear." (PMID 37901236, 2023). "Finally, the high expression level of ORC6 was associated with a decreased PFI in 13 types of cancers, including KIRP, LIHC, and PRAD." (PMID 36978046, 2023). "Our single-cell functional analysis also indicated a close association between ORC6 expression and DNA damage and repair mechanisms, which highlights the underlying mechanisms of aberrant ORC6 expression in cancer from both genetic alteration and epigenetic modification perspectives." (PMID 37901236, 2023). "Also overexpressed are three members of the origin recognition complex (ORC4, ORC5, ORC6) that were also previously linked to cancer development." (PMID 29416781, 2018). "The outcomes presented above clearly demonstrate the substantial anti-cancer effect following the silencing or KO of ORC6 in both primary and immortalized NSCLC cells." (PMID 39349930, 2024). "Next, we conducted a comprehensive analysis to understand the possible functional roles of ORC6 in pan-cancer studies (34 cancer types)." (PMID 39349930, 2024). "Bioinformatics studies highlighted ORC6’s potential pivotal role in cancer by influencing DNA synthesis and cell cycle progression." (PMID 39349930, 2024). "ORC6 emerges as a promising prognostic biomarker across various cancer types, particularly in LIHC and GBMLGG." (PMID 37901236, 2023). "In conclusion, this pan-cancer analysis comprehensively identified that the high expression of ORC6 predicts a poor prognosis, ORC6 participates in the MMR process, and ORC6 is correlated with immunomodulatory cells, cytokines, and genes." (PMID 36978046, 2023). "Meanwhile, further in-depth investigations based on the data from the present study are needed to explore the sophisticated functions of ORC6 and its relevant molecular mechanism in individual cancer." (PMID 36978046, 2023). "Nonetheless, the precise molecular mechanism of action of ORC6 in these cancers remains to be elucidated." (PMID 36978046, 2023). "In this study, we observed that the expression of ORC6 was higher in most tumors than in normal tissues, as well as in paired cancer and paracancerous tissues." (PMID 37901236, 2023).
cancer (continued). "In five different cancer types (ACC, ESCA, LIHC, KIRP, and PAAD), the ORC6 gene only exhibited “amplified” genetic variants." (PMID 37901236, 2023). "The ORC6 overexpression is correlated with worse prognostic outcomes in the majority of cancers (e.g., KIRC, LIHC, and PRAD) whereas it correlated with a better prognosis in COAD, OV and THYM." (PMID 36978046, 2023). "We performed a comprehensive pan-cancer study of ORC6 and revealed its important role in LIHC and GBMLGG." (PMID 37901236, 2023). "Further analysis of TCGA data revealed that ORC6 expression was significantly increased in tumor tissues versus adjacent normal tissues in 18 types of cancers, including BLCA, BRCA, and PRAD." (PMID 36978046, 2023). "The pan-cancer analysis demonstrated that ORC6 expression was significantly upregulated in 29 types of cancers, including BLCA, CESE and PRAD." (PMID 36978046, 2023). "Subsequently, to explore the relationship between ORC6 expression and genomic variations across different cancer types, we employed either the Wilcoxon rank-sum test or the Kruskal–Wallis rank-sum test." (PMID 37901236, 2023). "The results were interesting, as they showed that ORC6 was primarily expressed at high levels in the malignant cells of these cancers." (PMID 37901236, 2023). "The frequency and type of ORC6 gene genetic alterations across cancers were analyzed by the cBioPortal platform." (PMID 37901236, 2023). "We first investigated the ORC6 status in pan-cancer by analyzing the available data from TCGA, encompassing 33 most common types of cancers, including BLCA, CESE, and DLBC." (PMID 36978046, 2023). "The results indicated that high ORC6 expression level was simultaneously associated with low OS and DSS in 13 types of cancers (e.g., KIRC, KIRP and PRAD), while low ORC6 expression was associated with low OS and DSS in patients with OV." (PMID 36978046, 2023). "To further investigate the relationship between ORC6 and the functional status of different cancers, we analyzed single-cell sequencing data obtained from CancerSEA for 14 types of cancer." (PMID 37901236, 2023). "According to the TCGA database, the ORC6 expression level was inversely related to the infiltration level of cancer-related fibroblasts in seven types of cancers, including BRCA, LUSC, STAD, and TGCT." (PMID 36978046, 2023). "By examining ORC6 across cancers, we observed that it significantly contributes to the development of LIHC and GBMLGG." (PMID 37901236, 2023). "As far as we know, this is the first comprehensive analysis of the expression and biological function of ORC6 from a pan-cancer perspective." (PMID 36978046, 2023). "ORC6 expression level was positively correlated with TMB in 10 types of cancers, including LUAD, PRAD and STAD." (PMID 36978046, 2023). "In summary, ORC6 significantly influenced all survival metrics of only five types of cancers (i.e., BRCA, KIRP, LIHC, PAAD, and PRAD)." (PMID 36978046, 2023). "It is noteworthy that ORC6 was also involved in the MMR pathway in 14 types of cancers, including ESCA, GBM and PRAD." (PMID 36978046, 2023). "ORC6 expression was significantly upregulated in 29 types of cancers compared to the corresponding normal adjacent tissues." (PMID 36978046, 2023). "The OS analysis demonstrated that ORC6 expression level was as an unfavorable indicator for patients with 18 types of cancers (e.g., KIRC, KIRP and PRAD), and a protective marker only for patients with OV and THYM." (PMID 36978046, 2023). "ORC6 overexpression correlated with higher stage and worse prognostic outcomes in most cancer types analyzed." (PMID 36978046, 2023). "This correlation further supports the potential of ORC6 as a cancer regulatory factor and provides valuable clues for further exploring its role in cancer." (PMID 37901236, 2023). "ORC6 overexpression has been shown to promote cell proliferation, migration, and invasion of cancer cells." (PMID 35886011, 2022).
cancer (continued). "Incorrect pre-RC formation has been linked to impaired DNA damage repair pathways in humans, while both Orc6 and members of the Mcm2-7 complex have been shown to be reliable cancer biomarkers." (PMID 22738223, 2012). "Studies indicate that alterations in ORC6 expression or function may contribute to tumorigenesis and cancer progression in some certain cancers." (PMID 39349930, 2024). "The results collectively suggest that ORC6 is predicted to play a significant role in essential cellular processes such as mitosis, DNA synthesis, DNA repair, and cell cycle progression across various cancer types." (PMID 39349930, 2024). "The bioinformatics studies reveals that ORC6 could play a significant role in essential cellular process including mitosis, DNA synthesis and cell cycle progression in cancer." (PMID 39349930, 2024). "Comprehensive bioinformatics analyses across various cancers suggested that ORC6 might play a significant role in crucial cellular processes, such as mitosis, DNA synthesis and repair, and cell cycle progression." (PMID 39349930, 2024). "Recent research shows that ORC6 regulates the advancement of multiple cancers; however, it remains unclear what regulatory impact it has on the tumor immune microenvironment." (PMID 37901236, 2023). "Altogether, these results indicate that ORC6 may promote immunosuppression in a wide array of cancer types." (PMID 36978046, 2023). "Firstly, ORC6 plays an important role in tumorigenesis and may work as an independent prognostic biomarker for many types of cancers." (PMID 36978046, 2023). "Analysis of ORC6 protein levels using IHC staining results revealed similar results, confirming that ORC6 broadly participates in the tumorigenesis of different types of cancers." (PMID 36978046, 2023). "Additionally, the ORC6 mRNA expression level was positively correlated with copy number alteration (CNA) in 21 types of cancers, including BRCA, PRAD, and UCS." (PMID 36978046, 2023). "Current research on ORC6 in tumors is restricted to specific types of human cancers." (PMID 37901236, 2023). "Finally, according to PFI analysis, ORC6 high expression level acted as an unfavorable indicator for patients with 23 types of cancers (e.g., KIRP, LIHC and PRAD), and as a protective marker only in patients with GBM, OV, STAD, and THYM." (PMID 36978046, 2023). "The heatmap indicated that ORC6 was coexpressed with most immune-related genes across cancers." (PMID 37901236, 2023). "Further comparison of the ORC6 expression according to the TCGA database revealed that ORC6 expression was significantly increased in higher-stage tumor tissues than in lower-stage tumor tissues in 11 types of cancers, including ACC, KICH, and LUAD; however, it was decreased in OV and SKCM tissues." (PMID 36978046, 2023). "Additionally, ORC6 expression level was negatively correlated with tumor endothelial cell infiltration in 11 types of cancers, including ESCA, KIRC, LUAD, LUSC and STAD, while a positive correlation was observed in LGG." (PMID 36978046, 2023). "Six immune subtypes (e.g., C1: wound healing; C2: IFN-γ dominant; C3: inflammatory; C4: lymphocyte depleted; C5: immunologically quiet; C6: TGF-β-dominant) presented significantly different ORC6 expression levels in 15 types of cancers, including BRCA, LIHC, LUAD and PRAD." (PMID 36978046, 2023). "Interestingly, we found that ORC6 plays multifaceted roles during tumorigenesis, inhibiting or promoting tumor progression depending on the specific types of cancers." (PMID 36978046, 2023). "Therefore, molecular probes targeting ORC6 combined with multifunctional carriers are promising cancer treatment strategies." (PMID 37901236, 2023). "ORC6 is involved in the tumorigenic process of a limited number of cancer types." (PMID 36978046, 2023).
cancer (continued). "Collectively, these observations provide new insights into the complex regulation of immune cell-mediated tumor suppression and suggest that ORC6 may serve as a promising predictive marker of immunotherapy efficacy in cancer treatment." (PMID 37901236, 2023). "Altogether, these results imply that ORC6 expression level may predict the prognosis of cancer patients." (PMID 36978046, 2023). "Therefore, patient-specific cell lines and an Orc6-based mouse model of MGS should be useful for testing genome instability and the increased predisposition to cancer." (PMID 36012502, 2022). "The expression of ORC6 was further validated in clinical ccRCC samples and cancer cells." (PMID 35711825, 2022). "Furthermore, the chemokine CCL14 was negatively correlated with ORC6 expression across cancers." (PMID 37901236, 2023). "Together, our investigation provides a comprehensive understanding of the tumorigenic role of ORC6 in different cancers and indicates that ORC6 could be a dependable biomarker for predicting the clinical prognoses and immune landscapes in patients with LIHC and GBMLGG." (PMID 37901236, 2023). "In addition, ORC6 may be involved in multiple signaling pathways related to cancer progression and immune regulation." (PMID 37901236, 2023). "Our results indicated that the expression of ORC1, ORC2, ORC3, ORC4, ORC5, and ORC6 was different in the seven common types of tumor‐infiltrating immune cells, such as B cells, CD4 T cells, CD8 T cells, NK cells, macrophages, endothelial cells, and cancer‐associated fibroblasts." (PMID 36205357, 2023). "Furthermore, our data also showed that the ORC6 expression level is positively correlated with immunosuppressive and immunostimulatory genes across cancers, hinting that ORC6 may act as a potential immune checkpoint." (PMID 36978046, 2023). "Finally, ORC6 may tune the therapeutic outcome of immunotherapy via regulating immunomodulatory gene expression across cancers." (PMID 36978046, 2023). "Our data showed that GSEA demonstrated a strong correlation between ORC6 and MMR pathways in 14 types of cancers (e.g., PRAD, STAD, and KIRC)." (PMID 36978046, 2023). "The increased ORC6 expression was observed in 29 types of cancers, including BLCA, CESE, and PRAD, compared to the corresponding normal adjacent tissues while decreased ORC6 expression was observed only in LAML." (PMID 36978046, 2023). "Higher expression of ORC6 was significantly associated with worse prognosis in DSS for patients with 17 types of cancers (e.g., ACC, LGG and PRAD), while lower expression of ORC6 was only negatively correlated with the prognosis of COAD, OV, and THYM." (PMID 36978046, 2023). "Moreover, TCGA pan-cancer gene set enrichment analysis (GSEA) indicated a strong and positive correlation between ORC6 expression and mitosis, cell cycle progression, DNA repair and replication." (PMID 39349930, 2024). "Moreover, we observed a positive correlation between ORC6 expression and MYC target V2, MYC target V1, MTORC1, mitotic spindle, G2 checkpoint, E2F target, DNA repair, and other pathways across cancers." (PMID 37901236, 2023). "However, the prognostic value of ORC6 expression levels and its potential effect on processes related to tumor development, such as the regulation of the tumor microenvironment and immunosuppression, in a number of human cancers remain unknown and require further study." (PMID 36978046, 2023). "The GSVA score revealed that ORC6 was positively correlated with some cell proliferation pathways (e.g., G2M checkpoint, E2F targets and MYC targets v1–2), “DNA Repair” pathway and “unfolded protein response” pathway in almost all cancers." (PMID 36978046, 2023). "Our study revealed that ORC6 expression level was closely related with TMB in 10 types of cancers (e.g., LUAD, PRAD and STAD), with MSI in 11 types of cancers (e.g., PRAD, SARC and STAD), and with the expression of 5 MMR genes in a majority of cancers (e.g., HNSC, LIHC and PRAD)." (PMID 36978046, 2023).
cancer (continued). "Our data showed that ORC6 expression level was significantly related to different immune subtypes in 15 types of cancers (e.g., BRCA, LIHC, and PRAD); these data may partially explain why ORC6 plays different roles in the prognosis and immunotherapy response of diverse cancers." (PMID 36978046, 2023). "In addition, ORC6 was negatively correlated with several immune pathways (e.g., IL2-STAT5 signaling, inflammatory response and IL6-JAK-STAT3 signaling) in the majority of cancers." (PMID 36978046, 2023).